MT-CO2 (mitochondrially encoded cytochrome c oxidase II)
Description:
Component of the cytochrome c oxidase, the last enzyme in the mitochondrial electron transport chain which drives oxidative phosphorylation. The respiratory chain contains 3 multisubunit complexes succinate dehydrogenase (complex II, CII), ubiquinol-cytochrome c oxidoreductase (cytochrome b-c1 complex, complex III, CIII) and cytochrome c oxidase (complex IV, CIV), that cooperate to transfer electrons derived from NADH and succinate to molecular oxygen, creating an electrochemical gradient over the inner membrane that drives transmembrane transport and the ATP synthase. Cytochrome c oxidase is the component of the respiratory chain that catalyzes the reduction of oxygen to water. Electrons originating from reduced cytochrome c in the intermembrane space (IMS) are transferred via the dinuclear copper A center (CU(A)) of subunit 2 and heme A of subunit 1 to the active site in subunit 1, a binuclear center (BNC) formed by heme A3 and copper B (CU(B)). The BNC reduces molecular oxygen to 2 water molecules using 4 electrons from cytochrome c in the IMS and 4 protons from the mitochondrial matrix.
Synonyms: COX2; CO2; formerly MTCO2
Tractability: Small molecule: a structure with a bound ligand is known; a high-quality ligand is known; it belongs to a druggable protein family. Antibody: UniProt predicts a signal peptide or a membrane-spanning region. PROTAC: ubiquitination databases record sites on it; a small molecule that binds it is known.
Target class: Oxidoreduction-driven transporters; Primary active transporter; Transporter
Gene: Protein-coding gene on chromosome MT (7,586 to 8,269, forward strand). Ensembl gene ENSG00000198712.
Subcellular location: Mitochondrion inner membrane
Pathways (Reactome):
Metabolism: Complex IV assembly; Respiratory electron transport
Metabolism of proteins: Mitochondrial protein degradation; Mitochondrial translation termination
Cellular responses to stimuli: Cytoprotection by HMOX1
Gene Ontology:
Molecular function: cytochrome-c oxidase activity; protein binding; copper ion binding; oxidoreductase activity
Biological process: ATP synthesis coupled electron transport; cellular respiration; mitochondrial electron transport, cytochrome c to oxygen; electron transport chain; lactation; proton transmembrane transport; response to ethanol; response to hypoxia
Cellular component: membrane; mitochondrial inner membrane; mitochondrial membrane; mitochondrion; respiratory chain complex IV; mitochondrial matrix
Gene-disease validity (ClinGen):
ClinGen rates the evidence that MT-CO2 causes each of these diseases.
mitochondrial disease (mitochondrial): Definitive.
Leigh syndrome (mitochondrial): Limited. A progressive neurological disease defined by specific neuropathological features associating brainstem and basal ganglia lesions.
Homologues: Orthologues: chimpanzee MT-CO2 (98% identical), macaque COX2 (88% identical), pig COX2 (72% identical), rabbit MT-CO2 (72% identical), mouse mt-Co2 (71% identical), rat Mt-co2 (71% identical), guinea pig MT-CO2 (71% identical), tropical clawed frog COX2 (69% identical), zebrafish mt-co2 (66% identical), Drosophila melanogaster mt:CoII (56% identical), Caenorhabditis elegans WBGene00010965 (40% identical).
Diseases named in the same sentence as MT-CO2 in open-access papers:
MT-CO2 is named in the same sentence as 11 diseases in open-access papers, as found by Europe PMC text mining. Sharing a sentence is not in itself a finding about the gene and the disease. The quoted sentences say what the papers report.
melanoma (1 paper, 2020). A malignant, usually aggressive tumor composed of atypical, neoplastic melanocytes. "The same group also showed that two mitochondrial inner membrane proteins: cytochrome c oxidase subunit 2 (MT-CO2) and cytochrome c oxidase subunit 6C (COX6c) are enriched in the plasma of melanoma patients as well as in tumor tissues-derived EVs compared to healthy controls." (PMID 32331267, 2020).
MELAS (1 paper, 2025). "In primary fibroblasts from three independent MELAS patients, we found that activation of MNRR1 enhances mitophagy (as seen via LCB and pSer65 ubiquitin levels) and mitochondrial biogenesis (PGC1α, MTCO2, TOM20 levels)." (PMID 40710331, 2025).
mesothelioma (1 paper, 2023). A usually malignant and aggressive neoplasm of the mesothelium which is often associated with exposure to asbestos. "Other highly expressed genes in sarcomatoid mesothelioma cell lines were two ATP synthase subunits (ATP5H, ATPO), MTCO2, COX5B, COX 6C2, IDH3A, IDH3B and TIMM9." (PMID 37297007, 2023).
Parkinson disease (1 paper, 2022). A progressive degenerative disorder of the central nervous system characterized by loss of dopamine producing neurons in the substantia nigra and the presence of Lewy bodies in the substantia nigra and locus coeruleus. "In amygdala, the overall piRNAs-aligned pseudogenes ratio is not different in Parkinson’s disease, but some related pseudogene-aligned piRNAs, including HSP90, MTCO1, MTCO2, YWHAZ, GAPDH, and MTND were upregulated in the PD group." (PMID 35269612, 2022).
tumor (7 papers, 2012 to 2022). "When the protein extracts of the tumor tissues were analyzed by Western blotting, we observed a decrease in MTCO2 level in the drug-treated group, with the drug combination groups showing the most significant reduction of MTCO2 protein." (PMID 31277230, 2019). "Based on the standard plot obtained with predetermined numbers of 468LN cells expressing human mitochondrial marker MTCO2 measured with qRT-PCR, we approximated that on the average 2,000 468LN cells metastasized to the individual 468LN tumor draining lymph node." (PMID 22545097, 2012). "Finally, proteins involved in tumor migration, invasion, malignancy and cell adhesion (Ctsd or Cathepsin D, MTCO2, Tpd52l2, Rab5c, Smarcc1) were also found to be exclusively expressed or significantly up-regulated by the AI tumorspheres compared to the AD cells." (PMID 29298329, 2018). "To determine which tumour cell population relied most on high mitochondrial translation levels, we labelled primary tumour sections for the mitochondrial markers MTCO1 and MTCO2." (PMID 35768510, 2022).
cancer (2 papers, 2018 to 2019). A tumor composed of atypical neoplastic, often pleomorphic cells that invade other tissues. "Moreover, MTCO2 and Anxa2 were reported to be associated with radio-resistance and as biomarkers of cancer stem cells, respectively." (PMID 29298329, 2018). "For example, the prognostic impact of SOX9, SENP1 and mTOR was limited to ERG positive cancers while FOXA1, MTCO2 and FOXP2 were only prognostic in ERG negative cancers." (PMID 31606028, 2019).
brain disorder (1 paper, 2023). A disease affecting the brain or part of the brain. "Mitochondrial dysfunction has long been implicated in the pathogenesis of PD, and several studies have identified mutations in mt-Co2, mt-Co2, mt-Co3, and mt-Atp6 associated with various clinical brain disorders." (PMID 38041169, 2023).
MT-CO2 also shares sentences with these, for which no sentence is quoted: Asthenozoospermia (1 paper); hepatitis B (1); hepatitis C (1); measles (1).